CTLA4 (cytotoxic T-lymphocyte associated protein 4)
Diseases named in the same sentence as CTLA4 in open-access papers (continued):
Sharing a sentence is not in itself a finding about the gene and the disease.
tumor (continued). "Since the addition of anti-PD-1 to the tumor fragments produced established TIL cultures from three more patients than either the alone or anti-CTLA-4 conditions, we investigated how PD-1 interference would affect the TILs in rapid expansion protocol (REP)." (PMID 37359554, 2023). "In this study, anti-VEGF antibodies combined with anti-CTLA-4 therapy resulted in an increase in anti-tumor response resistant to the immunosuppressive effects of the ligand galectin-1." (PMID 37420216, 2023). "ICIs target inhibitory pathways in T-cells, such as the programmed death-1 (PD-1)/programmed death-ligand 1 (PD-L1) and cytotoxic T-lymphocyte-associated antigen 4 (CTLA-4) axes, thereby augmenting the anti-tumor immune response." (PMID 38234398, 2023). "Immune checkpoint inhibitors (CTLA-4, PD-1/PD-L1 based ICIs) have reformed cancer therapeutics by enhancing the immune response against tumor cells." (PMID 36677919, 2023). "One of the typical hallmarks of the tumor microenvironment is the up-regulation of inhibitory receptors including CTLA-4, TIM-3, PD1, LAG-3, and TIGIT on the surface of cytotoxic lymphocytes." (PMID 37629138, 2023). "The blockade of one of PD-1, LAG-3, and CTLA-4 showed compensatory upregulation of other immune checkpoint molecules, enhancing their ability to suppress local T cells in a tumor model study." (PMID 38026944, 2023). "In some cancer cells, redaporfin-PDT also increases CTLA-4 and PD-L1 expressions and virtuous combinations between PDT and immune-checkpoint blockers (ICB) depend on CD80/PD-L1 or CD80/CTLA-4 tumour overexpression ratios post-PDT." (PMID 37468749, 2023). "Three days after challenge with live SCC VII-Luc/GFP tumors, mice received blocking antibodies to either PD-1 or CTLA-4 by i.p. injection, and the effect on tumor outgrowth was measured." (PMID 37655661, 2023). "The immune checkpoints PD‐1 and CTLA‐4 were significantly upregulated in the rechallenged tumours after cryoablation." (PMID 37157934, 2023). "While its role under healthy conditions is to modulate T cell activity by inhibiting excessive T cell activation, CTLA-4, in the context of cancer, prevents the proliferation and activation of tumor-specific T cells." (PMID 38069095, 2023). "Immune-checkpoint inhibitors (ICIs), as a therapeutic target, prevent tumor cell evasion by acting as monoclonal antibodies against the CTLA-4 and PD-LA1 ligands." (PMID 37623035, 2023). "Monoclonal antibodies directed against CTLA-4, PD-1, and PD-L1 block these immune checkpoints and unleash anti-tumor immunity, leading to tumor cell death through cytolytic molecules." (PMID 37781307, 2023). "The use of inhibitors targeting immune checkpoint receptors, such as PD-1 and CTLA-4, has notably enhanced patient outcomes, enabling long-term tumor stabilization and even remission." (PMID 37372117, 2023). "Immune checkpoint inhibitors, such as PD-1 and its ligand, PD-L1, and CTLA-4, play an active role in the evasion of tumor surveillance and therapeutic resistance of MDS cells." (PMID 36600245, 2023). "Targeting the CTLA-4 pathway has been successful in tumour immunotherapy, however in more than 60% of patients, CTLA-4 blockade leads to multiorgan autoimmune reaction." (PMID 37173304, 2023). "In particular, our plant-produced anti-CTLA-4, together with Yervoy®, blocked the CTLA-4 function on tumor cells, leading to a marked inhibition of tumor growth as a result of T cell activation." (PMID 37711295, 2023). "These factors assist in maintaining immune homeostasis and safeguarding against autoimmunity; however, using PD‐1, PD‐L1, or CTLA‐4 monoclonal antibodies can be useful in upregulating T‐cell response against tumor cells." (PMID 38037752, 2023). "The DC-CIK cells displayed increased proliferation and IFN-γ production in vitro following stimulation with anti-CTLA-4, which intensified their lethal effect on the tumor cells." (PMID 36761751, 2023).
tumor (continued). "Mice harbouring intracranial GL261-Luc2 tumours were given a ketogenic diet and it was found that these mice had a significant reduction in immune inhibitory receptors such as PD-1 and CTLA-4 among their tumour-infiltrating lymphocytes." (PMID 37626597, 2023). "In mouse HCC models, the combination of ICIs (anti-CTLA-4 and anti-PD-1) with histone deacetylase inhibitor Belinostat induced early upregulation of PD-L1 on tumor antigen presenting cells and late expression of PD-1 on tumor infiltrating effector T cells." (PMID 38155974, 2023). "Further, this plant-produced anti-CTLA-4 2C8 mAb demonstrated similar antitumor efficacy with the commercial anti-CTLA-4 mAb (Yervoy®) in a humanized mouse tumor model." (PMID 37711295, 2023). "In the last years, three preclinical studies have tested an anti-CTLA-4 mAb labelled with [64Cu] to visualize CTLA-4 levels in tumor tissues." (PMID 38067379, 2023). "Treatment with anti-PD-1, anti-PD-L1 or anti-CTLA-4 revitalizes T cells and allows the adaptive immune system to target tumor cells." (PMID 37316840, 2023). "In syngeneic in vivo cancer models metformin enhanced the anti-tumour effect of anti-CTLA-4 therapy." (PMID 36823364, 2023). "Checkpoint molecules, such as PD-1 and CTLA-4, are expressed on T cells and can be activated by ligands expressed on tumor cells or other cells in the TME." (PMID 37175653, 2023). "This was further supported by other studies where administering CTLA-4 antibodies to mice with a pre-established B16-BL6 melanoma resulted in tumour clearance." (PMID 39086690, 2023). "Surprisingly, the expression of IRs such as PD-1 and CTLA-4 in tumor-infiltrated CD8+ T cells was simultaneously increased, which would facilitate ICI application." (PMID 37190284, 2023). "After elucidating the roles of these checkpoint molecules in tumor immune escape, therapeutic mAbs were developed to disrupt interactions between PD-1/CTLA-4 and their respective ligands on tumor and immune cells." (PMID 37958404, 2023). "This phenomenon, known as the tumor escape mechanism, involves the recognition of tumor cells by surface antigen receptors normally expressed on T cells, including PD-1 and CTLA-4." (PMID 37998743, 2023). "If the tumor cells activate immune checkpoint signaling pathways (e.g., CTLA-4 and PD-1), they can escape from CTLs attacks." (PMID 37790935, 2023). "Following results observed in other tumor types with ICI combinations, the association of an anti-PD1 and an anti-CTLA-4 was evaluated in unresectable MPM." (PMID 36902544, 2023). "When the CTLA-4 blocking rate is varied between u=0.93 and u=0.9315, the corresponding tumor size is 4.9361×105 and 8.1300×103, respectively." (PMID 36766849, 2023). "Nivolumab restores the functionality of anti-tumor T cells, while ipilimumab (a CTLA-4, cytotoxic T-lymphocyte antigen-4 inhibitor) induces responses in newly generated anti-tumor T cells." (PMID 37999824, 2023). "Oral and systemic administration of inosine can improve the efficacy of ICIs that target the immune checkpoint cytotoxic T lymphocyte-associated protein 4 (CTLA-4), thus reducing tumor weights and enhancing antitumor immunity." (PMID 35914737, 2023). "For instance, it has been discovered that the ACAT inhibitor avasimibe, the COX2 inhibitor celecoxib, and the specific EP4 antagonist E7046, when combined with PD-1 or CTLA-4 inhibitors, generate a synergistic anti-tumor immune response in mice tumor models." (PMID 36677919, 2023). "Immune checkpoints, such as PD1/PDL1 and CTLA4, are critical regulators of the immune response, and their overexpression in tumor cells is a well-known mechanism of immune evasion." (PMID 37511974, 2023). "The introduction of ICIs against programmed cell death protein-1 (PD-1) and cytotoxic lymphocyte antigen-4 (CTLA-4) has demonstrated an operative impact on the immune system to counter tumor cells within the TME." (PMID 37892995, 2023).
tumor (continued). "Agents that interfere with this interaction have demonstrated potent and durable anti-tumour activities, with less severe immune-related toxicity compared to CTLA-4 blockade." (PMID 37345033, 2023). "The combined blockade of CTLA-4 and PD-1 amplifies anti-tumor T cell responses and provides synergistic activity." (PMID 37927462, 2023). "The current study is focused on the analysis of regulatory T cell subsets and the CTLA-4 immune checkpoint, known to be responsible, at least in part, for tumour immune evasion." (PMID 36319895, 2023). "In the local tumor microenvironment, CTLA-4 expression has been seen to upregulate IDO1, which reciprocally promotes T-reg activation." (PMID 36879122, 2023). "CS was reported to induce ADAM12+ CTLA4+ Tregs (a unique subset of tumor-specific activated Tregs) which interact with exhausted T cells in the tumor immune environment of lung cancer." (PMID 37324952, 2023). "Other researchers also demonstrated that TTFields combined with anti-PD1/anti-CTLA-4/anti-PD-L1 therapy can significantly reduce tumor volume and increase the infiltration of cytotoxic T lymphocytes and memory CD8+ T cells in the tumor microenvironment." (PMID 38067345, 2023). "In this study, they assessed the effect on tumor inhibition of injection sequence, which showed that administration of free anti-CTLA-4 antibodies before Doxil had a better response compared to reversed order or concomitant with Doxil." (PMID 37106400, 2023). "Specifically, trials have combined GVAX with CTLA-4 in a bid to induce an anti-tumour T cell response." (PMID 37686543, 2023). "SPRYD4 also showed a close association with tumour-infiltrating lymphocytes and important immune checkpoints including PD1, PD-L1 and CTLA4 in CCA." (PMID 37142983, 2023). "Mechanistic studies showed that tumor-infiltrating CD8+ T cells (assessed by flow cytometry) increased by approximately fourfold after PD-1/CTLA-4 inhibition." (PMID 37120591, 2023). "Butyrate can also restrict the ability of dendritic cells to stimulate tumor-specific T cells and memory T cells, thus limiting the effectiveness of anti-CTLA-4 ICI (immune checkpoint inhibitor)." (PMID 37511612, 2023). "We were unable to establish TIL cultures from patients 7, 13, and 15 from tumor fragments that were unaltered, or with anti-CTLA-4." (PMID 37359554, 2023). "Following combination anti-CTLA4 treatment in multiple mouse tumor models, the immune response continued to attack the remaining tumor cells, and the inhibition of tumor metastatic behavior was observed." (PMID 37869003, 2023). "In particular, immune checkpoint inhibitors (ICIs) that target the programmed death-ligand 1 (PD-L1), programmed death 1 (PD-1), and cytotoxic T-lymphocyte-associated protein 4 (CTLA-4) pathways can restore T-cell functionality and promote anti-tumor immunity." (PMID 38077355, 2023). "PD1/PD-L1 and CTLA-4 are widely recognized as crucial immune checkpoints that play a key role in tumor immune escape." (PMID 37805556, 2023). "To investigate the predictive value of CTLA4 DNA methylation in HNSCC, we examined CTLA4 DNA methylation in tumor samples of N = 29 patients with advanced or metastatic HNSCC prior to ICB." (PMID 37415208, 2023). "Although the blockage of PD-1 and/or CTLA-4 can promote the activation of T cells and exert an effective anti-tumor function, the exuberant activation of self-reactive T cells with the resultant autoimmunity is presumed to be an irAE." (PMID 36891313, 2023). "Such approaches appear to have limited anti-tumor efficacy unless immune checkpoint inhibitors (Nivolumab, anti-PD-1 mAb; Ipilimumab, anti-CTLA-4 mAb) are used in reactivating residential T cells." (PMID 36977722, 2023). "A previous study reported that tumor-infiltrating CD4+ T cells can upregulate some immune checkpoint genes, including PD-1, T-cell immunoglobulin, mucin domain-3, cytotoxic T lymphocyte associated protein-4, and lymphocyte-activation-gene-3." (PMID 37007145, 2023).
tumor (continued). "Anti-programmed death receptor-1 (PD-1), anti-programmed death ligand-1 (PD-L1) and anti-cytotoxic T-lymphocyte protein 4 (CTLA4) have been developed to inhibit immune checkpoint pathways in order to prime anti-tumor activity of cytotoxic T-cells." (PMID 37760403, 2023). "Anti-CTLA-4 treatment has been reported to improve the infiltration of existing T cells in tumours with T-cell exclusion resistance mechanisms, thus improving responses to anti-PD-1 treatment." (PMID 37454231, 2023). "A lower tumor TIDE score was associated with a better ICB response and patient survival under anti-PD-1 and anti-CTLA-4 therapies." (PMID 36808166, 2023). "It has been proposed that, in addition to CD4+ T cells, the anti-tumor effects of anti-CTLA4 treatment depend, to some degree, on natural killer (NK) cell-mediated anti-tumor immunity." (PMID 36068918, 2023). "More complex dynamic interactions between OV, tumor cells, CTLA-4 and other types of cytokines and immune responses will be considered in our future research." (PMID 36766849, 2023). "The combination of radiotherapy and anti-CTLA-4 therapy activates T cells with TCR against tumor cells repertoires and the combination of immune checkpoint inhibitor and radiation/chemotherapy has been clinically applied in unresectable stage III NSCLC." (PMID 36895477, 2023). "To conclude, LPS-Nb36 has a stronger antigen-binding ability than Nb36 and can more efficiently block the CTLA-4 signal pathway of CTLs activated by the DC/tumor fusion vaccine." (PMID 37419930, 2023). "ES has been reported in patients who received tumor vaccines, adoptive cell metastasis therapy, or anti-CTLA-4 therapy." (PMID 37081866, 2023). "These antibodies reverse PD-1/CTLA4-mediated glycolytic inhibition, thus reinvigorating the anti-tumor activity of tumor infiltrating CD8+ T cells." (PMID 36765614, 2023). "Tumor cells target inhibitory receptors of effector and cytotoxic T cells such as PD-1 and the cytotoxic CTLA-4 by their ligand PD-L1/PD-L2 and CD80 on their surface." (PMID 36816749, 2023). "In the current study, we found that tumor-derived EVs triggered the overexpression of CTLA-4 on the surface of CD8 + T-cells." (PMID 37884996, 2023). "The expression of CTLA-4 has been demonstrated in lymphoid and myeloid cells as well as tumor cells." (PMID 37110545, 2023). "In this mechanism, the PD-1 inhibitor, PD-L1 inhibitor, and CTLA-4 inhibitor contribute to suppressing tumor cell development and increasing T cell activity." (PMID 36674491, 2023). "The developing HPV-driven tumor cells can upregulate immune checkpoint molecules, such as PD-1/PDL1, and CTLA-4, which negatively regulate cytotoxic T cells, blocking anti-tumour specific responses." (PMID 36960048, 2023). "The surfaces of tumour cells exhibit low CTLA-4 expression, but PDT increases CTLA-4 expressions in B16F10 and 4T1 cells." (PMID 37468749, 2023). "By targeting CTLA-4, Ipilimumab shuts down one of the inhibitory pathways that block effective anti-tumor responses." (PMID 37324191, 2023). "This regimen is based on the immunomodulatory role of CTLA-4 inhibitor (ipilimumab) in depleting tumor-infiltrating Tregs, followed by the adoptive transfer of CIML NK cells." (PMID 36932395, 2023). "Checkpoint inhibitors against CTLA-4 and PD-L1 have been cloned into oncolytic adenoviruses and have shown to be effective in controlling tumor growth with a high safety profile." (PMID 39086690, 2023). "This would indicate that inhibitors of the PD-L1/PD-1 axis and CTLA-4 would act at different stages of the process of anti-tumor immune activation." (PMID 38283359, 2023). "Blockades of these receptors such as PD-1 and CTLA-4 can reverse the state and reactivate the immune response thereby stopping tumor progression, suggesting the great potential of immune checkpoint blockade therapies in this regard." (PMID 37006257, 2023).
tumor (continued). "ICIs are typical immunotherapies that activate anti-tumor immunity by inhibiting negative regulatory receptors such as PD-1 and cytotoxic T lymphocyte antigen 4(CTLA4)." (PMID 37316840, 2023). "Radiotherapy increases the levels of immune checkpoints (PD-1, CTLA-4) locally in the tumor by enhancing the activation and infiltration of immune cells into the TME and the level of PD-L1 expression on the surface of tumor cells." (PMID 37546397, 2023). "Alternative checkpoints, such as v-domain immunoglobulin inhibitory T-cell activation (VISTA) and indoleamine 2, 3-dioxygenase 1 (IDO1), inhibit the tumor-killing function of T cells in addition to PD-L1 and CTLA-4." (PMID 36810098, 2023). "Studies were performed on CT26 colon cancer in mice, where tumor CTLA-4 and PD-1 blockade failed, likely depending on the MDSC function." (PMID 37373091, 2023). "A cyclic peptide targeted to the immune checkpoint protein CTLA4 is designed using a hierarchy of computational methods, demonstrated to bind by a physical measurement, and shown to inhibit tumor growth in cell culture and in mice." (PMID 37122540, 2023). "and the selective clearance of CTLA-4+ Treg cells has been shown to result in complete tumor regression in a mouse model." (PMID 37055849, 2023). "Intriguingly, fulvestrant in combination with the ICI, α-CTLA-4, modestly but significantly reduced tumor growth." (PMID 37312163, 2023). "Tumor immune checkpoint blockade immunotherapy targeting PD-1/PD-L1 or CTLA-4 prolongs the overall survival of cancer patients." (PMID 36714030, 2023). "Studies have shown that HIFU treatment led to an upregulation of immune checkpoint molecules, such as PD-1, PD-L1 or CD80/86 (ligand of CTLA-4) on tumor cells, dendritic cells (DC) or T Cells, resulting in better control of the tumors." (PMID 37180717, 2023). "This form of resistance revitalizes tumor growth even after an initial successful response to immunotherapy including nivolumab (a PD-1 inhibitor) and ipilimumab (a CTLA-4 inhibitor)." (PMID 38136402, 2023). "In the present study, the tumor microenvironment of the high-grade MCTs showed moderate or intense immunolabeling for all proteins (PD-L1, CTLA-4, RANK/RANK-L, and IFN-γ)." (PMID 37370399, 2023). "CTLA-4 inhibitors can stop T cell depletion and increase the anti-tumor T cell response by preventing the interaction between CTLA-4 and CD80/86 ligands." (PMID 37895012, 2023). "When Pd-L1 (ligand for Pd 1) and CTLA4 are upregulated, tumor cells can evade the immune response and promote tumor growth." (PMID 37980541, 2023). "The TME is classically distinguished by PD-L1 overexpression by tumor cells and CTLA-4 and PD-1 overexpression by T cells." (PMID 37047684, 2023). "Anti-CTLA-4 antibodies substantially increase the immune system's ability to suppress tumor growth and improve the prognoses of patients with cancer when used alone or in combination with other therapeutic agents." (PMID 38406785, 2023). "EV-targeted tumor therapies have been proposed because they can carry several immunosuppressive molecules, such as CTLA-4, PD-L1, TGF-β1, FasL, and TRAIL, which make them possible candidates for developing targeted therapies." (PMID 37884996, 2023). "Dendritic cell-mediated B7 signaling plays a critical role in the antitumor immune response, and we further tested the role of antigen expressing cells such as dendritic cells and macrophages in the tumor regression with anti-PD-1/CTLA-4/Ly6C treatment." (PMID 37449205, 2023). "For example, the combination of curcumin and anti-CTLA-4 therapy enhanced the anti-tumor effects via inhibition of PD-L1 and COP9 signalosome 5 compared to the single treatment group." (PMID 37622107, 2023). "In the BRCA1(−) tumor model, CTLA4 blockades combined with PARPi induce protective anti-tumor immunity and significant survival benefit by locally inducing anti-tumor immunity and increasing levels of IFNγ." (PMID 36900418, 2023).